TGFB1 (transforming growth factor beta 1)
Diseases named in the same sentence as TGFB1 in open-access papers (continued):
Sharing a sentence is not in itself a finding about the gene and the disease.
tumor (continued). "Using a 3D spheroid-based detachment assay, we found that MCF-7 cells treated by CM of TNFα + TGFβ1-stimulated MSCs (Group 4) had very high capabilities of scattering out of the 3D tumor spheroids." (PMID 28553282, 2017). "In the light of tumor–stroma autophagy model, we wanted to confirm that autophagy activation in response to tumor-secreted TGFβ1 in MEFs followed a gradient." (PMID 28515430, 2017). "Soluble platelet-derived factors (mainly TGFβ1) and direct physical contact with tumour cells (activating NF-κB pathway) work synergistically to induce EMT and subsequent migration and metastasis." (PMID 28737696, 2017). "TGFB1 protein showed moderate correlation with histopathological diagnosis (r = 0.427, p = 0.006) and tumor grade (r = 0.441, p = 0.004)." (PMID 29104726, 2017). "Transforming Growth Factor- beta 1 (TGF-β1) is a pleiotropic cytokine suggested to be the main inducer of tumor epithelial-to-mesenchymal (EMT) transition and to facilitate invasion by suppressing the host immune system." (PMID 28633655, 2017). "Humor tumor-derived exosomes, as immune inhibitory, exosomal delivery of TGFβ1 to T cell or NK cell lead to down-regulation of NKG2D expression." (PMID 28402944, 2017). "Platelets through direct contact or release of Transforming growth factor beta 1 (TGFβ1) can activate epithelial-mesenchymal transition (EMT) in tumour cells, an important step in cancer metastasis." (PMID 29064388, 2017). "TGFβ1 also suppresses normal epithelial cell proliferation during repair, and is thus considered a tumor suppressor." (PMID 28832494, 2017). "The role of TGFβ1 in tumor development in vivo showed that antisense TGFβ1 oligonucleotides reduced tumor growth considerably in mice xenografted with SCC9 cells." (PMID 28708091, 2017). "Our analysis revealed for the first time that MGUS is characteristic by low levels of TGFB1 and high levels of midkine, a heparin-binding growth factor involved in angiogenic and anti-apoptotic functions and tumor expansion in various cancers." (PMID 29050213, 2017). "The effect of TGFβ1 as a tumor promoter reflects its ability to induce EMT, which contributes to the invasion and migration of cancer cells." (PMID 28404892, 2017). "Several mechanisms have been suggested explaining how cancer cells impair NK cell functions, such as TGFβ-1 production by tumor cells, or the production of histamine and reactive oxygen species by phagocytes." (PMID 28210257, 2017). "Combinatorial approaches that aim to neutralize the effects of tumor-derived factors on exogenously administered DC, such as local siRNA-mediated silencing of TGFβ1 at the tumor site, have also been effective." (PMID 29209327, 2017). "The tumor angiogenesis is controlled by a large number of proangiogenic factors such as transforming growth factor beta 1 (TGF-β1), transforming growth factor alpha (TGF-α), and vascular endothelial growth factor (VEGF)." (PMID 28293063, 2017). "Our model predictions revealed a common impact of E2F1 and TGFB1 signaling on tumor invasiveness in both cancer types." (PMID 28775339, 2017). "Tumour-resident DCs exhibited pronounced upregulation of Mapkapk2 by 1.9-fold as compared to splenic DCs and also expressed high levels of Il10, Tgfb1 and Arg1, suggesting robust immunosuppressive activity of these cells within the TME." (PMID 28924177, 2017). "This idea has been translated to clinical studies of tumor-infiltrating lymphocytes engineered to express a TGFβ1-dominant negative transgene (NCT01955460)." (PMID 29312333, 2017). "Of note, the transcript of pro‐fibrotic cytokine TGFβ1 was increased in tumor cells of relapsing mice." (PMID 27974353, 2017). "TGFβ1, one of the important cytokines, acts as a suppressor early in tumor progression, whereas it acts as a tumor promoter in later stages." (PMID 28404892, 2017). "FNI is known to induce tumor metastasis, and TGFB1 acts as proto-oncogene which can induce cell growth when mutated." (PMID 28793339, 2017).
tumor (continued). "Especially in the responder tumor overexpressed transcripts include the growth factors TGFB1 (log 2fc=−2.07) and TGFB1/1 (log 2fc=−3.27) themselves, as well as their direct pathway targets SMAD3 (log 2fc=−2.44) and SMAD7 (log 2fc=−3.86)." (PMID 28594404, 2017). "For instance, TGFβ1 in B16-F10 tumor-conditioned media is capable of preventing DC differentiation from bone marrow precursors and instead drives MDSC differentiation through upregulation of the Id1 transcriptional regulator." (PMID 29209327, 2017). "TGFβ1 is a master regulator of the epithelial to mesenchymal transition, a process that enables tumor invasion and cancer metastasis." (PMID 28404898, 2017). "Aberrations occurring in the TGFβ1 and Wnt/β-catenin signalling pathways have both been implicated in EMT and tumour progression." (PMID 28223538, 2017). "Control tumor cells were grown in parallel with medium alone (Group 1) or with TNFα + TGFβ1 only (Group 2)." (PMID 28553282, 2017). "TGFβ1 and TGFβ2 can either act as a tumor promoter in diverse cancer models or as a tumor suppressor by inhibiting cell proliferation." (PMID 29221185, 2017). "The study also identified MYC, HNF4A and TGFB1 as top upstream regulators correlating to tumor tissue content." (PMID 28445515, 2017). "We propose a mechanism for brain metastasis whereby a soluble factor in the microenvironment of the primary tumor (e.g. TGFβ1) induces the expression of intracellular or extracellular proteins (e.g. ANGPTL4) in cells of the primary tumor." (PMID 29100268, 2017). "The tumor sizes in the mice injected with the TGFβ1 antagonist were significantly smaller than those in the SKOV-3 with CAF group." (PMID 29221185, 2017). "Total TGFβ1 levels were high in both groups and increased in tumor-bearing mice as compared to tumor-free mice." (PMID 29123081, 2017). "In parallel, TGFβ1-stimulated MSCs release factors that act directly on tumor cells and promote their invasive properties." (PMID 28553282, 2017). "Transforming growth factor-beta 1 (TGF-β1) suppresses T cell function, promoting tumor immune escape." (PMID 27626488, 2016). "This is important as TGFβ1 promotes immunosuppressive effects on various effector T-cells and induces tumour-promoting phenotypes in both neutrophils and macrophages." (PMID 27515461, 2016). "On the other hand, tumor exosomes have also the ability to induce immune suppression by activating CD4+/CD25+Foxp3+ regulatory T cells (Treg) via TGFβ-1." (PMID 26861306, 2016). "Emerging data support TGFβ1 as a major modulator of tumor progression through regulation of endothelial cell proliferation and migration, extracellular matrix metabolism, epithelial-to-mesenchymal transition (EMT) and metastasis." (PMID 27542226, 2016). "In this review, we discussed the indirect effects on tumour progression exerted by αv integrins because of their ability to activate latent TGFβ1." (PMID 27515461, 2016). "TGFβ1-dependent tumour suppression is attributable mostly to the direct effects of the inhibition of epithelial cell division by the activation of cyclin-dependent kinase inhibitors (p21, p15 Ink4b)." (PMID 27515461, 2016). "Tregs accumulate and expand in the tumor microenvironment and produce excessive interleukin 10 (IL-10) and TGFβ1." (PMID 27270649, 2016). "Still other tumor cells have been reported to overexpress the SMAD7 inhibitory SMAD (I-SMAD) that competitively inhibits TGFβ1-mediated SMAD signaling." (PMID 27589814, 2016). "3T3 murine fibroblasts expressed ∼20-fold more TGFβ1 than either the PanIN or IC21 cells, consistent with the stroma source of TGFβ1 in the tumor microenvironment." (PMID 27058416, 2016). "Again, the data were consistent with the αvβ6 activation of TGFβ1 driving tumour cell invasion except that, this time, the αvβ6-positive “microenvironmental” myoepithelial cell promoted the invasive phenoptype." (PMID 27515461, 2016).
tumor (continued). "Strikingly, Wnt7a was as effective as TGFβ1 treatment in generating 4T07 tumours containing a substantial population of activated CAFs in the tumour core." (PMID 26777421, 2016). "In fact, early studies showed that, in normal tissues, αvβ6 was tumour-suppressive through its activation of TGFβ1." (PMID 27515461, 2016). "Quantification of the expression levels of miR-122, TGFβ1 and TGFβR1 in these tissue samples revealed an eightfold decrease in miR-122 expression and an eightfold increase in the TGFβR1 level in tumour samples." (PMID 26987776, 2016). "Immunohistochemistry also confirmed higher TGFb1 staining in tumor cells in PC3-ERRα compared to PC3-CT-induced bone lesions in vivo and in PC3c-ERRα compared to PC3c-CT-induced bone lesions in vivo." (PMID 27776343, 2016). "VEGF-A, WNT5A and TGFβ1 were upregulated by ERRα in tumor cells and all of these factors also significantly and positively correlated with ERRα expression in CRPC patient specimens." (PMID 27776343, 2016). "In this review, we will combine those data and extrapolate from a combination of in vitro and clinical observations to infer the likely roles of integrin-dependent TGFβ1 regulation of the tumour stroma." (PMID 27515461, 2016). "TGFβ1-treated fibroblasts can secrete osteopontin, an RGD-containing integrin ligand implicated in the promotion of tumour growth, EMT and metastasis." (PMID 27515461, 2016). "This review focuses on TGFβ1’s contribution to tumor immune suppression and escape, with emphasis on the influence of this regulatory cytokine on the differentiation and function of dendritic cells and T cells." (PMID 27589814, 2016). "These decreases in both tumour weight and angiogenesis were compromised when TGFβ1 was overexpressed in HepG2-122." (PMID 26987776, 2016). "Anti-tumor T cell responses have also been shown to be inhibited by TGFβ1 derived from cells of myeloid origin." (PMID 27589814, 2016). "The expression of TGFβ1 in tumor and plasma was found to be significantly higher in patients with colorectal cancer and was correlated with tumor stage." (PMID 27681738, 2016). "Integrin activation of latent TGFβ1 can be a significant component of the way that tumours develop and respond to their stroma." (PMID 27515461, 2016). "Eventually, we will establish the role of αvβ6 and, indeed, the role of other αv integrins in activating TGFβ1 in each of these cancers and the subsequent effects on tumour growth and spread." (PMID 27515461, 2016). "The dichotomy of TGFβ1’s anti-proliferative yet pro-tumor activities can be explained by the acquisition of tumor cell resistance to the negative regulatory effects of this cytokine during tumor progression." (PMID 27589814, 2016). "Taken together, these results demonstrate that TGFβ1 is a key immunosuppressive factor that confers tumor cell resistance to NK cells." (PMID 27589814, 2016). "In contrast, the global knockout mice showed significantly reduced tumour progression, suggesting that TGFβ1 signalling in the stroma normally promoted pancreatic neoplasia." (PMID 27515461, 2016). "Several other independent studies have also reported elevated TGFβ1 expression within tumor tissue or plasma of patients with various cancers." (PMID 27589814, 2016). "Transforming growth factor β1 (TGFβ1) is a pleiotropic cytokine that can function as both tumour suppressor and tumour promoter (for reviews, see Inman 2011; Yang and Moses 2008; Roberts and Wakefield 2003)." (PMID 27515461, 2016). "Strong data also describe the way that TGFβ1 regulates the tumour microenvironment (TME) to regulate cancer progression." (PMID 27515461, 2016). "Evidence for how TGFβ1 contributes to the advancement of tumors is conflicting and appears to be dependent on the developmental stage of the tumor." (PMID 27144026, 2016). "Recent findings from several other groups have also shown that TGFβ1 induces tumor-promoting functions in DC." (PMID 27589814, 2016).
tumor (continued). "On the other hand, increased levels of TGFβ1 also promotes tumor cell proliferation, leading to increased tumor formation." (PMID 27270649, 2016). "Small molecule inhibitors of TGFβ1 receptor have been reported to reduce the oncogenic activity of TGFβ1, such as epithelial to mesenchymal transition and tumor metastasis." (PMID 26769851, 2016). "Collectively, these deleterious effects of TGFβ1 on DC development and function significantly compromise the quality of anti-tumor immune responses and can be a major contributing factor to tumor immune escape." (PMID 27589814, 2016). "In the same study, treatment with TGFβ1 switched off dormancy, leading to rapid tumour growth in vivo, suggesting that TGFβ2 alone is a mediator of dormancy." (PMID 27782035, 2016). "While TGFB1 was induced in the tumour, its activators integrins and THBS1 were upregulated in both cell types, highlighting the reciprocal crosstalk between the two cell types to regulate cell adaptation and tissue remodeling." (PMID 27049916, 2016). "Previously we have shown that TGFβ1 was the key player involved in tumors of old hosts involved in the inhibition of tumor progression." (PMID 26497558, 2015). "Lastly, expression levels of TGFβ1 in the spleens were determined because of their relevance to the previous study performed directly on the tumor." (PMID 26253138, 2015). "According to the tumor tissue specimens’ weight in vitro before and after TGFβ-1 infectedhMSC intervention, the tumor weight inhibition rate was calculated." (PMID 26003220, 2015). "A recent study suggests that tumor cell EMT is mediated through factors secreted from CAFs and that selective inhibition of TGFβ1 is sufficient to reverse EMT associated gene expression." (PMID 26268945, 2015). "The highest tumor inhibition rate of MHCC97-L animal models was observed in the fifth week after TGFβ-1 infected hMSC engraftment, and the tumor inhibition rate gradually reduced with the prolongation of time." (PMID 26003220, 2015). "As a tumor growth stimulating factor, TGFβ-1 plays an important role in tumor growth, invasion, and metastasis." (PMID 26003220, 2015). "The results indicate a reduced responsiveness of tumour cells to TGFβ, a preferential up-regulation of TGFB1 in malignant tumours and a preferential up-regulation of TGFB3 in premalignant tumours." (PMID 26703884, 2015). "hMSC and TGFβ-1 infected hMSC exhibit anti-tumor activity in a time-dependent manner, and the activity against HCC gradually reduces with the prolongation of time." (PMID 26003220, 2015). "TGFβ1 expression in tumor cells was a marker of poor prognosis regarding DMFS (HR = 2.28; 95 % CI: 1.4 to 3.8; p = 0.002), DFS (HR = 2.00; 95 % CI: 1.25 to 3.5; p = 0.005) and OS (HR = 1.89; 95 % CI: 1.04 to 3.43; p = 0.037)." (PMID 26040677, 2015). "We have also recently shown that B16-F1-derived TGFβ1 alters that maturation and activation of tissue-resident DC and promotes their acquisition of a phenotype that is likely to favor tumor progression." (PMID 26441959, 2015). "For late stage tumors, TGFβ1 is known to be tumor promoter and help facilitate more aggressive tumors." (PMID 26497558, 2015). "Previously published results demonstrated from transcriptome analysis on the tumor that TGFβ1 was a key molecule involved in the tumor dynamics." (PMID 26253138, 2015). "Within the tumor masses, abundant populations of vimentin and Transforming Growth Factor β1 (TGFβ1) positive tumor cells can be visualized." (PMID 25970777, 2015). "We previously showed the effects of tumor progression as a function of age, where it was revealed that old hosts provide an environment for the retarded tumor progression with TGFβ1 being the key player involved within the tumor." (PMID 26497558, 2015). "TGFβ1 is important for maintaining homeostatic control of growth in premalignant and early-stage carcinogenic cells, which allow TGFβ1 to act as a tumor suppressor." (PMID 26253138, 2015).
tumor (continued). "The TGFβ1 expression pattern in the spleen of tumor-bearing mice closely mirrored that of the recognized key genes." (PMID 26253138, 2015). "Subsequently, Pang at al. used the same mouse model and showed that TGFβ signaling in myeloid cells is indeed essential for tumor metastasis by regulating the production of type II cytokines, TGFβ1, arginase 1, and iNOS." (PMID 25629162, 2015). "In the multivariate analysis, and when adjusted to age, SBR grade, tumor size, and lymph node invasion the co-expression of TGFβ1 and TIF1γ remained an independent poor prognostic factor that predicted metastasis, any recurrence and death from any cause." (PMID 26040677, 2015). "In the animal models test, we demonstrated that hMSC and TGFβ-1 gene infected hMSC exhibit anti-tumor activity in a time-dependent manner, and the activity against HCC gradually reduces with the prolongation of time." (PMID 26003220, 2015). "We demonstrated directly from tumor tissue (which contains both tumor and stromal components) that TGFβ1 was decreased in tumors of older hosts." (PMID 26497558, 2015). "We can recognize several further microRNAs positively correlated with TGFβ role as a supporter of tumor growth: miR-21, shown to be induced by TGFβ1 and to target SMAD7, thus leading to the TGFβ-promoted formation of cancer associated fibroblasts." (PMID 26188123, 2015). "This molecular network shows that TGFβ1 can not only directly influence the migration of tumor cells, but also indirectly influence the movement of tumor cells by controlling the expression of cell matrix proteins and skeletal proteins." (PMID 25793716, 2015). "TGFβ1 is critically involved in cancer initiation and progression through tumor cell autonomous signaling and interactions with the tumor microenvironment." (PMID 24670043, 2014). "Transforming growth factor β1 (TGFβ1) plays a dual role in cancer biology, in both tumor suppression and tumor promotion." (PMID 25149540, 2014). "The lower effect of the tumour cell supernatants on αSMA expression is due to the lower concentration of active TGFβ1 in the supernatant compared with the activity of rTGFβ1." (PMID 27919042, 2014). "TGFβ1 plays opposing roles in tumor progression depending upon the stages of the disease, leading to protection during normal development versus promotion/progression at the premalignant/carcinoma transitions." (PMID 25526025, 2014). "This pathway includes well-known cancer-related genes such as FOS, TGFB3 and TGFB1 that increased connectivity in the tumor network." (PMID 25253512, 2014). "As known to all, TGFβ1 acts as both promoter and repressor via different cell signaling in tumor pathogenesis." (PMID 25162823, 2014). "VEGF is also augmented by mediators produced by TAM and tumor cells 11 such as transforming growth factor beta 1 (TGFβ1) and other factors, such as IL-13, IL-4, and IL-10 6, skewing the macrophage response toward an M2 phenotype." (PMID 24421272, 2014). "Tumour cell-derived TGFβ1 increased the generation of myofibroblastic cells, which promote the invasion of tumour cells in an in-vitro 3D model and which can be prevented by redox-active nanoparticles (stromal therapy)." (PMID 27919042, 2014). "The role of TGFβ-1 in cancer progression has been shown to be multifaceted, depending on the tumor stage." (PMID 24891760, 2014). "TGFB1’s growth inhibition is believed to be replaced by tumor-promoting functions, i.e., immunosuppression and angiogenesis, in more advanced tumors, where its expression is in fact increased." (PMID 24472434, 2014). "TGFβ1-exposed PCa cells were also co-cultured with phorbol 12-myristate 13-acetate (PMA)-treated THP-1 macrophages as a model of the tumor microenvironment." (PMID 25202359, 2014). "A growing body of evidences showed that TGFβ1 functions as either a tumor suppressor or a tumor promoter via both SMAD (drosophila mothers against decapentaplegic protein)-dependent and SMAD-independent cascades." (PMID 25162823, 2014).